RNY3P7 (RNY3 pseudogene 7)
Gene: Miscellaneous RNA gene on chromosome 13 (77,623,372 to 77,623,472, forward strand). Ensembl gene ENSG00000206800.
Homologues: Orthologues: chimpanzee Y_RNA (99% identical), macaque Y_RNA (96% identical). Paralogues in human: Y_RNA (89% identical), Y_RNA (88% identical), RNY3 (87% identical), Y_RNA (87% identical), RNY3P1 (86% identical), Y_RNA (86% identical), Y_RNA (85% identical), RNY3P14 (84% identical), Y_RNA (84% identical), Y_RNA (83% identical), RNY3P11 (82% identical), RNY3P9 (82% identical), and 96 more.